GDF5 (growth differentiation factor 5)
Diseases named in the same sentence as GDF5 in open-access papers (continued):
Sharing a sentence is not in itself a finding about the gene and the disease.
acromesomelic dysplasia (4 papers, 2008 to 2019). A group of extremely rare, inherited, progressive skeletal conditions that result in a particular form of short stature, called short-limb dwarfism. "Such connections are the Hunter-Thompson and Grebe types of acromesomelic dysplasia, both of which are caused by a mutation in the GDF5 gene." (PMID 31044086, 2019). "For example, fibular hypoplasia and complex brachydactyly are also closely associated with acromesomelic dysplasia types, and arise from a mutation in the same gene, GDF5, even though these diseases do not appear together in the literature and have low comorbidity." (PMID 31044086, 2019).
lumbar disc degeneration (4 papers, 2011 to 2024). "rs224329, also situated in the GDF5 gene, this SNP has been associated with chronic low back pain and lumbar disc degeneration." (PMID 39722795, 2024). "Single nucleotide polymorphisms (SNPs) at IL-1β, MMP3, TGF-β1, and GDF5 have been associated with risk of a wide variety of diseases, such as keratoconus, chronic periodontitis, and lumbar disc degeneration." (PMID 28676856, 2017). "Variations in GDF5 have been linked to OA and lumbar disc degeneration." (PMID 39722795, 2024).
myocardial infarction (4 papers, 2021 to 2024). Gross necrosis of the myocardium, as a result of interruption of the blood supply to the area, as in coronary thrombosis. "Indeed, GDF5 was previously linked to cardiac repair after myocardial infarction in mice." (PMID 34021165, 2021). "In vivo ablation of BMP14 (also known as GDF5) results in increased cardiomyocyte apoptosis, fibrosis and adverse cardiac remodeling after myocardial infarction in adult mice." (PMID 34692797, 2021).
Parkinson disease (4 papers, 2012 to 2022). A progressive degenerative disorder of the central nervous system characterized by loss of dopamine producing neurons in the substantia nigra and the presence of Lewy bodies in the substantia nigra and locus coeruleus. "A number of TGFβ superfamily members are neuroprotective, such as BMP7 in cerebral ischemia and GDF5 in Parkinson's disease." (PMID 24586579, 2014).
brachydactyly type A2 (3 papers, 2014 to 2026). Brachydactyly type A2 (BDA2) is a congenital malformation characterized by shortening (hypoplasia or aplasia) of the middle phalanges of the index finger and, sometimes, of the little finger. "GDF5 mutation R380Q can lead to brachydactyly type A2; M173V/L176P/S204R/R301stop can all lead to brachydactyly type C; R378Q can lead to Du Pan syndrome." (PMID 29371961, 2017). "Most mutations result in the deactivation of GDF5, causing the abnormal skeletal development seen in disorders such as Brachydactyly type A2." (PMID 29371961, 2017). "Recently was published the role of activating and deactivating mutations in the receptor interaction site of GDF5 in the development of symphalangism or brachydactyly type A2." (PMID 25024859, 2014).
intervertebral disc degeneration (3 papers, 2018 to 2024). "A model of intervertebral disc degeneration induced by acupuncture on the tail of rats was constructed, and the repair effect of composite hydrogels with GDF5-loaded microspheres combined with NPSCs on IDD was observed." (PMID 38200442, 2024). "Additionally, GDF-5 plays a crucial role in intervertebral disc degeneration by inhibiting apoptosis of nucleus pulposus cells, promoting the synthesis of key ECM components, and downregulating the expression of proinflammatory factors, thus alleviating intervertebral disc degeneration." (PMID 39639374, 2024).
joint disease (3 papers, 2013 to 2023). "In accordance, research has linked mutations of GDF-5 to multiple cartilage and joint disorders." (PMID 36943593, 2023). "GWAS associations and our functional studies above indicate that the highly localized control of GDF5 expression level is important for a myriad of human joint disease risks." (PMID 34230488, 2021). "Yet, the specificity of GDF5 effect also makes it a fruitful target for joint-specific intervention, as is (already) required in the treatment of most cases of joint disease, which are often localized and not systemic." (PMID 34230488, 2021).
Osteopenia (3 papers, 2019 to 2023). Osteopenia is a term to define bone density that is not normal but also not as low as osteoporosis. "Effects of hydroxyapatite (HA) particles with bone morphogenetic BMP-2 or GDF-5 were compared in sheep lumbar osteopenia; in vitro release in phosphate-buffered saline (PBS) or sheep serum was assessed by ELISA." (PMID 35203721, 2022). "Recently, GDF-5 (also referred to as BMP-14) has shown positive effects in a sheep model of lumbar osteopenia by enhancing middle to long-term bone formation via changes in bone structure, formation, resorption, and compressive strength." (PMID 31484306, 2019). "This suggests that a BMP-2 dose of ~250 μg may be sufficient for long-term induction of bone formation in the present system, close to the 100 μg recommended for BMP-2, GDF-5 and its mutant BB-1 in the sheep defect model of lumbar osteopenia." (PMID 37378714, 2023). "The present study shows that combined delivery of HA and low-dose BMP-2 (1 μg) or GDF-5 (5 μg) is highly suitable for the therapy of lumbar osteopenia in aged sheep, including long-term augmentation of bone structure and bone formation, as well as biomechanical stabilization." (PMID 35203721, 2022).
rheumatoid arthritis (3 papers, 2016 to 2021). A chronic, systemic autoimmune disorder characterized by inflammation in the synovial membranes and articular surfaces. "Variants in growth differentiation factor 5 (GDF5) have been reported to be associated with rheumatoid arthritis (RA) in several ethnic populations." (PMID 27662846, 2016). "In vitro stimulation of TNF caused a reduction in GDF‐5 expression in rheumatoid arthritis and OA fibroblasts compared with unstimulated cells respectively, however, another critical pro‐inflammatory factor, IL‐1β, revealed no change in GDF‐5 expression in OA fibroblasts." (PMID 33522652, 2021).
brachydactyly type A1 (2 papers, 2013 to 2024). A rare, congenital limb malformation characterized by shortened or underdeveloped middle phalanges of all digits, that are sometimes fused with the terminal phalanges. "Here, we report on a family with an autosomal dominant inherited combination of SYNS2 and additional brachydactyly type A1 (BDA1) caused by a single point mutation in GDF5 (p.W414R)." (PMID 24098149, 2013).
brachydactyly type C (2 papers, 2008 to 2017). "Type C brachydactyly (MIM 113100) is a skeletal disorder caused by GDF5 mutation, and some patients with type C brachydactyly also present with dysplasia of hip joints." (PMID 18947434, 2008).
breast tumors (2 papers, 2012 to 2023). "Two peptides, previously used in another study of our laboratory, inhibited breast tumor TGFß-dependent angiogenesis in vitro and in vivo by inhibition of TGFß signaling and of the subsequent TGFß-dependent GDF5 overproduction in EC." (PMID 23226264, 2012).
Kashin-Beck disease (2 papers, 2014 to 2015). Disabling osteochondrodysplasia with osteosclerosis, cone-shaped metaphysis, and shortening of the diaphysis. "A previous study examining the association between GDF5 gene polymorphisms and Kashin-Beck disease found that the polymorphism of haplotype TGC is associated with KBD." (PMID 25997002, 2015).
liposarcoma (2 papers, 2013 to 2014). A usually painless malignant tumor that arises from adipose tissue. "We have previously shown that the AEI of rs143383 is increased after AZA induced demethylation of GDF5 in the heterozygous SW872 human liposarcoma cell line." (PMID 24861163, 2014). "We used the human liposarcoma cell line SW872 for our research since 1) the cell line expresses GDF5; 2) it is heterozygous for rs143383; 3) it also demonstrates GDF5 DAE and 4) it is amenable to a variety of in vitro experimental manipulations." (PMID 23825960, 2013).
lymph node metastasis (2 papers, 2023 to 2024). "Recently, GDF5 has been also found to be associated with lymph node metastasis in colorectal cancer." (PMID 39150915, 2024).
multiple synostoses syndrome 2 (2 papers, 2013 to 2021). Any multiple synostoses syndrome in which the cause of the disease is a mutation in the GDF5 gene. "GDF5 gain-of-function mutations increase the downstream signalling of GDF5 causing proximal symphalangism (SYM) and multiple synostoses syndrome type 2 (SYNS2; MIM 610017) which is characterised by the fusion of the carpals, tarsals and vertebrae." (PMID 34573339, 2021).
synovitis (2 papers, 2022 to 2025). Inflammation of a synovial membrane. "Taken together, these findings reinforce our observation that obese patients are at a higher risk of more severe KOA, as synovial GDF5 expression correlates with disease severity and synovitis is more prevalent in individuals with higher BMI." (PMID 41465193, 2025).
chondrosarcoma (1 paper, 2013). A malignant cartilaginous matrix-producing mesenchymal neoplasm arising from the bone and soft tissue. "In line with that observed in SW872 cells, the increases in GDF5 expression were not significant following Sp1, Sp3 and P15 depletion but a significant fold change was observed upon DEAF-1 knockdown in this chondrosarcoma cell line." (PMID 23825960, 2013).
co-infection (1 paper, 2013). "However, co-infection of NOG suppressed chondrogenesis effectively in wild type GDF5 expressing cells, while GDF5W414R infected cells displayed a clear insensitivity towards NOG." (PMID 24098149, 2013).
developmental delay (1 paper, 2024). "Loss of GDF5 function results in developmental delay and a shortened appendicular skeleton." (PMID 39161420, 2024).
emphysema (1 paper, 2023). "We also found the adipocyte-specific BMPR2 knockout mice to spontaneously develop lung injury and emphysema, in which adipsin and GDF5 might be involved in the pathogenesis." (PMID 37886639, 2023).
endometrial cancer (1 paper, 2023). Primary or metastatic malignant neoplasm involving the endometrium (mucous membrane that lines the endometrial cavity). "employed transcriptome sequencing technology to analyze 5 pairs of endometrial cancer tissues and normal endometrial tissues, revealing downregulation of ID1, IGF1, GDF7, SMAD9, TGF-β, and WNT4 expression alongside upregulation of GDF5, INHBA, and ERBB4 in endometrial cancer." (PMID 38239355, 2023).
enthesopathy (1 paper, 2023). "The present studies demonstrate that both Hyp and C–/– entheses have increased expression of Gdf5, suggesting that enhanced GDF5 action contributes to the increased BMP and IHH signaling in Hyp and C–/– entheses and, thus, enthesopathy development." (PMID 37490334, 2023).
gastric cancer (1 paper, 2016). A primary or metastatic malignant neoplasm involving the stomach. "Though the regulatory connection between miR-132-3p and FOXO1 has already been reported in gastric cancer cells, the direct targeting of miR-132-3p with GDF5 and SOX6 was newly discovered." (PMID 27556448, 2016).
Hearing impairment (1 paper, 2013). A decreased magnitude of the sensory perception of sound. "However, joint fusions caused by NOG mutations often affect the ossicles leading to hearing impairment, whereas mutations in GDF5 including GDF5W414R spare this feature." (PMID 24098149, 2013).
Hematuria (1 paper, 2025). The presence of blood in the urine. "Patients with systemic lupus erythematosus showed higher levels of GDF5 compared to healthy controls, positively correlated with hematuria and disease activity, and was inversely associated with C3 and C4." (PMID 41303556, 2025).
hemochromatosis (1 paper, 2020). A disorder of iron metabolism characterized by a triad of HEMOSIDEROSIS; LIVER CIRRHOSIS; and DIABETES MELLITUS. "The juvenile hemochromatosis-causing mutation, Gly99Arg, in RGMCND and a corresponding mutation, Gly101Arg, in RGMBND attenuated the interactions with GDF5, Kd > 20 μM and > 150 μM, respectively." (PMID 32576689, 2020).
ischemic stroke (1 paper, 2025). A stroke disorder caused by obstruction of blood flow to the brain, due to thrombotic (local blood clot formation) or embolic (due to a blood clot or other material traveling from another site) event. "Increased expression of growth/differentiation factor-5 (GDF5) and platelet-derived growth factor subunit A (PDGFA) is observed following tDCS in a mouse model of ischemic stroke." (PMID 40438568, 2025).
metastatic cancer (1 paper, 2025). A carcinoma which has spread from the original site of growth to another anatomic site. "Growth differentiation factor-5 (GDF5) regulates TGFβ-mediated pro-angiogenic signaling, and its significant downregulation in the late stages here might set the stage for metastatic cancer." (PMID 41048341, 2025).
migraine (1 paper, 2023). "Of the 25 overlapping genes/loci, 6 genes/loci were associated with more than 2 phenotypes in HPGDB (COMT, OPRD1, IL1A, IL1B, TSPAN2/NGF, GDF5), and 15 genes were associated with migraine." (PMID 37144689, 2023).
nonalcoholic fatty liver disease (1 paper, 2021). "Here, we further investigated the effects of systemic overexpression of the GDF5 gene in adipocytes HFD-induced nonalcoholic fatty liver disease (NAFLD)." (PMID 33542911, 2021).
oral squamous cell carcinoma (1 paper, 2025). "In this regard, the study of a different set of immune markers - CK18 and GDF5 - in oral squamous cell carcinoma demonstrated how the expression levels of epithelial and differentiation markers provide prognostic insight and reflect the underlying immune and differentiation status of tumors." (PMID 41035646, 2025).
tendinopathy (1 paper, 2025). "Autologous mesenchymal/stromal stem cells (MSCs) and tendon-derived stem cells (TSCs), combined with growth factors (GFs) like GDF-5, GDF-6 and GDF-7, are emerging as potential therapies for tendinopathy." (PMID 40395976, 2025).
vitamin D deficiency (1 paper, 2023). A nutritional condition produced by a deficiency of VITAMIN D in the diet, insufficient production of vitamin D in the skin, inadequate absorption of vitamin D from the diet, or abnormal conversion of vitamin D to its bioactive metabolites. "This discovery suggests that genetics may play a crucial role in the development of KOA and a possible link between a decrease in GDF-5 and vitamin D deficiency in its pathophysiology." (PMID 38060707, 2023). "Our findings revealed a significant relationship between the GDF-5 T>C (rs143383) gene polymorphism, a reduction in GDF-5 protein, and vitamin D deficiency in obese Saudi women with KOA." (PMID 38060707, 2023).
tumor (9 papers, 2012 to 2023). "In contrast, in our studies of pathological tumor angiogenesis, we did not observe a compensatory increase in expression of BMP10 (or the close family member GDF5) within tumor lysates." (PMID 27741515, 2016). "In addition to these, BMP2, BMP6 and GDF5 were highly expressed in the TNBC tumours compared with tumours of other subtypes." (PMID 37333824, 2023). "The results from human tissue verification of the two target genes showed that the gene expression level was lower in EBVaGC compared with that in non-tumor tissues for GDF5 (P = 0.043), and marginal difference was also observed between EBVaGC and EBVnGC (P = 0.076)." (PMID 30258285, 2018). "Targeting GDF5 may also leave intact some of the anti-tumor activities of TGFß, while blocking pro-tumor activities." (PMID 23226264, 2012). "Among 11 BMPs, BMP3 and BMP8A expression levels were upregulated, and 5 BMPs (BMP2, BMP5, GDF5, BMP6, and GDF10) downregulated in tumor tissues compared with normal tissues." (PMID 34745928, 2021). "The histological verification experiment showed differential expressions of the two main target genes GDF5 and CXCL10 between EBVaGC and non-tumor tissues as well as EBVnGC." (PMID 30258285, 2018). "In addition, in the histological verification experiment, differential expressions of the two main target genes GDF5 and CXCL10 were observed between EBVaGC and non-tumor tissues as well as EBVnGC." (PMID 30258285, 2018).
cancer (7 papers, 2018 to 2025). A tumor composed of atypical neoplastic, often pleomorphic cells that invade other tissues. "GDF5 has been shown to be a downstream target of the TGF-beta signaling pathway, stimulating angiogenesis required for the growth and spread of the cancer." (PMID 31277598, 2019). "Cell‐cell signaling pattern between basal cancer cells (Ca), FPCS, and TPCS revealed that while Ca‐Ca and Ca‐FPC signaling mainly comprised PGF, TGFA, and VEGFA signaling, TPCS uniquely received BMP signals (BMP2/4 and GDF5) from Ca." (PMID 38582099, 2024). "Specific reports for HNSCC may not be available for all the genes of interest but published studies clearly document the cancer involvement for MMP24, EIF6 FAM83C and GDF5." (PMID 29371888, 2018).
degenerative diseases (4 papers, 2018 to 2024). "The polymorphism on rs143383 is located in the 5’ non-coding region of GDF-5 gene and is thought to yield downregulation of GDF-5 gene expression, ultimately yielding an increased onset risk of IVD degenerative disease." (PMID 39287911, 2024).
skeletal diseases (3 papers, 2009 to 2019). "The GDF5 mutations N445K,T are associated with an inherited skeletal disease characterized by joint fusions in fingers, toes and elbows." (PMID 19956691, 2009). "GDF5 mutations have previously been associated with several kinds of inherited skeletal diseases." (PMID 29371961, 2017).
skeletal dysplasia (2 papers, 2018 to 2021). Any Mendelian diseases that affects growth and development of the skeleton. "Different types of skeletal dysplasia resulted due to mutation in the GDF5 genes." (PMID 29643884, 2018).
infection (1 paper, 2013). The state of being infected such as from the introduction of a foreign agent such as serum, vaccine, antigenic substance or organism. "The endogenous Gdf5 mRNA level was concomitantly increased in the micromass cultures by the infection of RCAS virus encoding SOX11." (PMID 23356643, 2013).
metabolic disorders (1 paper, 2024). "The relationship between different genetic variants and BMI in KOA patients has been shown, among which there are a large number of genes associated with metabolic disorders (FTO, ADIPOQ, LEP, SREBP2) and other genes (GDF5, TGFB1, etc.)." (PMID 38424630, 2024).
GDF5 also shares sentences with these, for which no sentence is quoted: developmental dysplasia of the hip (8 papers); diabetes (2); genetic disorders (2); hand osteoarthritis (2); hip osteoarthritis (2); atrial fibrillation (1); BOR syndrome (1); celiac disease (1); Cerebral ischemia (1); Cognitive impairment (1); colorectal cancer (1); Congenital hip dislocation (1); congestive heart failure (1); coronary artery disease (1); craniosynostosis (1); dwarfism (1); dysplasia (1); end stage renal disease (1); fibrosis (1); gout (1); heart disorder (1); hip dislocation (1); Hypertension (1); idiopathic pulmonary fibrosis (1); Insulin resistance (1); melanoma (1); microcephaly (1); multiple synostoses syndrome type 1 (1); ovarian carcinoma (1); sarcopenia (1).
A further 7 diseases each share a sentence with GDF5 in 1 paper.